ZNF10 (zinc finger protein 10)
Description:
May be involved in transcriptional regulation.
Synonyms: KOX1
Tractability: Antibody: the Human Protein Atlas places it where antibodies can reach. PROTAC: ubiquitination databases record sites on it.
Gene: Protein-coding gene on chromosome 12 (133,130,349 to 133,159,465, forward strand). Ensembl gene ENSG00000256223.
Subcellular location: Nucleus
Subcellular location (Human Protein Atlas): Plasma membrane; Vesicles; Nucleoplasm
Pathways (Reactome):
Gene expression (Transcription): Generic Transcription Pathway
Gene Ontology:
Molecular function: protein binding; DNA-binding transcription factor activity, RNA polymerase II-specific; RNA polymerase II transcription regulatory region sequence-specific DNA binding
Biological process: regulation of transcription by RNA polymerase II; regulation of DNA-templated transcription
Cellular component: nucleus; protein-containing complex
Genetic constraint (gnomAD): Loss-of-function variants: 8 observed, 11.98 expected, observed/expected ratio (o/e) 0.67, 90% interval 0.39 to 1.2. The upper end of that interval is the gene's LOEUF score, 1.2, which puts it in group 5 of 6, group 1 being the genes least tolerant of losing a copy. Missense variants: 600 observed, 709.7 expected, observed/expected ratio (o/e) 0.85, 90% interval 0.79 to 0.9. Synonymous variants: 229 observed, 240.51 expected, observed/expected ratio (o/e) 0.95, 90% interval 0.85 to 1.06.
Homologues: Orthologues: chimpanzee ZNF10 (99% identical), dog ZNF10 (87% identical), rabbit ZNF10 (86% identical), guinea pig ZNF10 (82% identical), pig ZNF10 (81% identical), Drosophila melanogaster CG3281 (22% identical), Drosophila melanogaster CG2712 (21% identical), Drosophila melanogaster Phs (17% identical). Paralogues in human: ZFP37 (42% identical), ZNF180 (41% identical), ZNF266 (39% identical), ZFP90 (38% identical), ZNF674 (37% identical), ZNF25 (37% identical), ZNF555 (36% identical), ZNF264 (35% identical), ZNF805 (35% identical), ZNF875 (35% identical), ZNF169 (35% identical), ZNF599 (35% identical), and 50 more.
Diseases named in the same sentence as ZNF10 in open-access papers:
ZNF10 is named in the same sentence as 4 diseases in open-access papers, as found by Europe PMC text mining. Sharing a sentence is not in itself a finding about the gene and the disease. The quoted sentences say what the papers report.
head and neck squamous cell carcinoma (2 papers, 2021 to 2022). A squamous cell carcinoma that arises from any of the following anatomic sites: lip and oral cavity, nasal cavity, paranasal sinuses, pharynx, larynx, and salivary glands. "However, a study in head and neck squamous cell carcinoma described a characteristic promoter methylation pattern of ZNF10, TMPRSS12, ERGIC2, and RNF215 genes, which was proposed as a biomarker of response to radiotherapy treatment." (PMID 35359376, 2022). "ZNF10 promotes the carcinogenesis and progression of breast invasive ductal carcinoma via the Wnt/β-catenin signaling pathway and recently was identified as a component of a radiotherapy-related four-gene signature that predicts the survival of head and neck squamous cell carcinoma patients." (PMID 34638319, 2021).
Headache (1 paper, 2023). Cephalgia, or pain sensed in various parts of the head, not confined to the area of distribution of any nerve. "Recent GWAS analysis from the UK Biobank showed that the loss-of-function of ZNF10 and ZNF382 is associated with a high risk of headache and corneal hysteresis, respectively, although it is unclear whether these are direct consequences of derepressed expression of LINE-1 transcripts." (PMID 37680368, 2023).
cancer (4 papers, 2021 to 2023). A tumor composed of atypical neoplastic, often pleomorphic cells that invade other tissues. "An additional case comes from ZNF10, which has a function in promoting cancer progression, it is likely that the hyper-DMCs in H3K9me3 regions nearby ZNF10 has potential to contribute to human healthy aging by inhibiting tumorigenesis." (PMID 37181094, 2023). "The regulatory network analysis revealed that ZNF10, a transcriptional repressor protein, was MTERF2’s potential target in 10 cancers." (PMID 34030708, 2021). "Similar to ZFP57, our data demonstrate that the level of ZNF10 is not related to KIRC patients’ survival, although it is negatively associated with cancer stemness." (PMID 34638319, 2021).
ZNF10 also shares sentences with these, for which no sentence is quoted: breast invasive ductal carcinoma (1 paper).